BCL2 (BCL2 apoptosis regulator)
Diseases named in the same sentence as BCL2 in open-access papers (continued):
Sharing a sentence is not in itself a finding about the gene and the disease.
colon carcinoma (continued). "Lactobacillus acidophilus and Bifidobacterium bifidum showed increased cytotoxic effects against breast and colon cancer cell lines by upregulating Bax, IFN-γ, and TNF-α expression and downregulating Bcl2 expression." (PMID 35054452, 2022). "Colon cancers, especially adenocarcinoma, often harbor high levels of HCMV, with IE1 and pp65 present in 82% and 78% of colorectal cancer samples with increased expression of Bcl-2 and COX-2 proteins, thus promoting colon cancer progression." (PMID 35458542, 2022). "Not only inhibits the expression of Bcl-2, increases the expression of Bax, and induces caspase-dependent apoptosis, but also inhibits EMT and affects the growth of colon cancer RKO cells." (PMID 36686745, 2022). "The cell-bound exopolysaccharide of probiotics can potentially activate autophagy in colon cancer cells by stimulating Beclin1/GRP78 and the core regulators of intrinsic apoptosis pathway—Bcl-2 and Bak proteins." (PMID 35054452, 2022). "In a similar study, when apigenin was used in combination with the BCL2 inhibitor navitoclax for 48 h, there was an upregulation of BAX and BIM gene expression and protein levels, which led to apoptotic cell death in colon cancer (HTC-116) cells." (PMID 35614109, 2022). "We have shown that cytotoxic activity of a Wnt pathway inhibitor PP is more effective in combination with a pro-apoptotic Bcl-2 inhibitor (ABT737/ABT263) in killing colorectal cancer cells in vitro and in a xenografted human colon tumor in vivo." (PMID 36860494, 2022). "We have been able to confirm in colon cancer cells that increased DLG2 results in an increase in BAX and a decrease in BCL2 resulting in lower cell proliferation." (PMID 35499706, 2022). "β-sitosterol reduced the expression of both Bcl-2 and “cellular inhibitor of apoptosis protein-1” (cIAP1), while inducing the activation of BAX and cytochrome C in the human colon cancer cells HT116." (PMID 34679718, 2021). "Here we show that the methyltransferase WHSC1 is also highly expressed in colon cancer samples, and WHSC1 bind to BCL2 gene promoter, changing the H3K36me2 modification state to increase its transcription." (PMID 33469000, 2021). "Colon cancer CSCs overexpress LGR5, which results in increased numbers of antiapoptotic Bcl-2 and BcL-xL genes." (PMID 34577576, 2021). "Under hypoxia in colon cancer cells, the HIF-1α-dependent expression of miR-210 ensured the radioprotective mechanism involving autophagy and Bcl-2." (PMID 33806538, 2021). "H3K36me2, expressions of multiple oncogenes (ADAM9, EGFR, Sox2, Bcl-2, SYK, and MET) and Akt activation were significantly decreased after NSD2 silencing or knockout in primary colon cancer cells." (PMID 34671018, 2021). "In colon cancer cells, these HCMV-specific proteins contribute to the induction of Bcl-2 and COX-2 proteins thus promoting colon cancer progression." (PMID 34566995, 2021). "Treatment of HCT116 colon cancer cells with 70 μg/ml of C. orbiculata extract resulted in an increase in the co-precipitation of hnRNPA2B1 with BCL2L1, BCL2, MDM2, cMYC, CD44, CDK6, and cJUN mRNA." (PMID 33163396, 2020). "Mechanistically, FAL1 interacts with STAT3 and triggers its phosphorylation to modulate the expression of Bcl-2, TGF-β1, p65, and PCNA in colon cancer cells." (PMID 33246471, 2020). "We determined BCL-2 protein profiles in DLD-1 and HCT 116 colon cancer cells by quantitative Western Blotting." (PMID 33066609, 2020). "The CaCo-2 colon cancer cell line, in contrast to DLD-1 and LOVO, was revealed to overexpress the Bcl-2 and Bcl-xL proteins." (PMID 32392733, 2020). "Colon cancer cells treated with carnosol had reduced viability, increased apoptosis, increased pro-apoptotic BAX expression and decreased anti-apoptotic Bcl-2 expression." (PMID 33049974, 2020).
colon carcinoma (continued). "(B) Spearman’s rank correlation coefficient (rs) between the mean H-scores of β-catenin and p68, Bcl-2, Bcl-xL, Survivin and XIAP was determined from both normal and colon carcinoma tissues in combination." (PMID 31351496, 2019). "(A) Scatter plots representing the mean H-scores of β-catenin and p68, Bcl-2, Bcl-xL, Survivin and XIAP in normal (n = 22) and colon carcinoma tissue (n = 45) samples, respectively." (PMID 31351496, 2019). "The abundance of Bcl-2, Bcl-xL, Survivin and XIAP were enhanced in colon carcinoma samples compared to normal." (PMID 31351496, 2019). "Apoptosis induction via targeting of BCL2, BCL2L12, and Mcl-1 in colon cancer cells by miR-125a-5p is another aspect of the tumor suppressive role of this miRNA." (PMID 31887997, 2019). "Curcumin as an anticancer agent has been reported to induce apoptosis, reduce survival and able to down-regulate Bcl-2, VEGF, cyclin D1, pro-oncogenic factors and NF-κB in colon cancer cells." (PMID 31108984, 2019). "NF-κB and Bcl-2 have been suggested to play important roles in the activation of PPAR-γ and apoptosis in human colon cancer cells." (PMID 31354797, 2019). "This study found that colon cancer cells exposed to DEHP or MEHP exhibited increased cell viability and increased levels of P-glycoprotein, CD133, Bcl-2, Akt, ERK, GSK3β, and β-catenin when treated with oxaliplatin or irinotecan, as compared to control." (PMID 29568348, 2018). "In the current study, we found that the administration of Epo with LFM-A13 resulted in increased apoptosis in both colon cancer lines, as evidenced by the clear increase in the BAX/BCL-2 ratio." (PMID 29690619, 2018). "With these important targets of miR-15a, (BCL2, BMI1, YAP1 and DCLK1) in colon cancer having potential to promote colon cancer growth, we investigated the effects of miR-15a on cell proliferation." (PMID 29416778, 2018). "We further revealed this impact on colon cancer stem cells was due to the inhibition of E2F3, and BCL2 by Western immunoblot analysis." (PMID 29507661, 2018). "In BGC-823, SGC-7901, and MGC-803 cell lines and in human colon cancer HT-29, HCT-116, SW480, casticin induced apoptosis intrinsically by down regulation of c-FLIP, Bcl-2, x-IAP, and survivin." (PMID 30597838, 2018). "In vitro studies have reported that EPA and DHA induced apoptosis in the colon cancer cell lines HT-29, Caco-2, and DLD-1 through an increase in caspase-3 activity and inhibition of Bcl-2." (PMID 29760813, 2018). "Previous studies have shown that mir-129 suppresses expression of BCL2, TS, and E2F3 in colon cancer." (PMID 29507661, 2018). "As in colon cancer, also TNBC cells display overexpression of the BCL2 proteins at different rates;17,18 tumors often present BCL2 gene amplification and this relates itself to increased protein levels." (PMID 29352235, 2018). "Our results showed that siHuR decreased transcriptional expressions of galectin-3, β-catenin, cyclin D1, Bcl-2, P-gp, MRP1, and MRP2 in epirubicin-treated colon cancer cells." (PMID 28968471, 2017). "MMPP (0-15 μg/mL) enhanced the expression of apoptotic proteins such as Bax, cleaved caspase-3 and cleaved caspase-8 while decreased the expression of anti-apoptotic protein Bcl-2 in HCT116 and SW480 colon cancer cells." (PMID 29207641, 2017).
colon carcinoma (continued). "Combination of MG with GLOI silencing exerts synergistic inhibitory effects on colon tumorigenesis and colon cancer growth mediated through up-regulation of STAT1 and Bax and down-regulation of Bcl-2." (PMID 28903386, 2017). "In colon cancer cells, DIM was shown to activate caspases-3, -7, -8, and-9, increase translocation of cytochrome c, while also reducing the anti-apoptotic Bcl-2 protein." (PMID 25706292, 2015). "The induction of apoptosis in colon cancer cells by 3BP was confirmed by the downregulation of XIAP, cIAP1, cIAP2, Mcl-1, and Bcl-2 protein levels and the upregulation of Bax protein level." (PMID 26054380, 2015). "In addition, miR-145 may also block the expression of Fli-1 and Bcl-2 in colon cancer cells." (PMID 24923427, 2014). "In accordance with those studies, our data also showed the increased Bax/Bcl-2 ratio, activated Caspase-3, and cleaved PARP in HS7-treated HT-29 colon cancer cells." (PMID 21423639, 2011). "In addition, miR-34a has an inhibitory effect on NOTCH1, NOTCH2, and NOTCH4 expression in pancreatic ductal carcinoma, whereas, in colon carcinoma, its inhibition rescued the expression of NOTCH1, NOTCH2, and BCL2." (PMID 40149537, 2025). "Similarly, fisetin suppressed the protein levels of antiapoptotic Bcl-XL and BCL-2 and increased proapoptotic BAK and BIM in HCT-116 colon cancer cells." (PMID 41180483, 2025). "The authors conclude that upregulation of Bcl-2 reduced the survival fraction of colon cancer cells after radiation treatment (4 Gy) which was not related to apoptosis." (PMID 37961749, 2024). "Also, BCL-2 (B-cell lymphoma 2) family proteins such as Bcl-2 and BAX gene expression were altered in colon cancer cell lines." (PMID 39372197, 2024). "In our study, ADAP1‐NOC4L overexpression increased cell motility and invasiveness, which was in the same way as MMP9, BCL2 expression, and BAX downregulation and thus could be inferred to be effective in colon carcinoma cell metastasis." (PMID 35702822, 2023). "In the present study, total Bcl-2 levels and Beclin-1–Bcl-2 complex formation decreased upon treatment of colon cancer cells with the KRG extract, both indicating the participation of the Bcl-2 signaling pathway in the KRG extract-induced autophagy-mediated cell death." (PMID 36079818, 2022). "DDMP-induced apoptosis in colon cancer cells (SW620 and HCT116) via the modulation of the activity of NF-KB, where it suppressed the anti-apoptotic genes (BCL2), whereas it induced the expression of the apoptotic genes (BAX, cleaved caspase-3 and cleaved PARP)." (PMID 35956468, 2022). "Our extensive qPCR results support the conclusion that the Bcl2 gene is stably expressed at the mRNA level in human colon cancer cells regardless of the treatment with plant toxin gossypol, bacterial endotoxin LPS, or cottonseed-derived bioactive extracts." (PMID 36364387, 2022). "These expression differences among them make Bcl2 rather than Gapdh or Rpl32 a preferable qPCR reference for colon cancer cells." (PMID 36364387, 2022). "The conclusion that Bcl2 is a suitable reference gene for qPCR analysis of gene expression in human colon cancer cells is confirmed with this comparison regardless of the cells treated with seed coat or kernel extract." (PMID 36364387, 2022).
colon carcinoma (continued). "Allicin can induce apoptosis in the colon cancer HCT116 cell line via the mitochondrial-dependent pathway, as it results in an increase in CYCS and apoptosis regulator BAX protein level but a reduction in the expression of the anti-apoptotic protein BCL2." (PMID 36497321, 2022). "Similarly, glandless cottonseed kernel extract treated human colon cancer cells and SYBR Green qPCR analyzed mRNA levels of 55 genes with BCL2 mRNA as the internal reference and 1% DMSO treatment as the sample control." (PMID 35058516, 2022). "For example, the treatment of the colon cancer cell lines HT-29 and DLD-1 with AOAA increased their sensitivity to 5-fluorouracil (5-FU), lowering cell colony formation, Bcl-2 expression, and viability, while increasing cell S-phase accumulation, apoptosis, cytochrome C release, and Bax expression." (PMID 35366284, 2021). "Colon cancer stem cells (CSCs), however, no longer require BCL-2 and depend mainly on BCL-XL for their survival." (PMID 34117376, 2021). "Moreover, after treating colon cancer cell HCT116 at concentrations of 60, 90, and 120 μM for 24 h by kaempferol, the expressions of RelA and apoptosis-related proteins Bax and Bcl2 were detected by WB." (PMID 34867383, 2021). "Therefore, our results indicated that BCL2 is a direct target gene of WHSC1, WHSC1 promoting BCL2 transcription by controlling the H3K36 dimerization modification in its transcription initiation region, so as to regulate colon cancer cell apoptosis." (PMID 33469000, 2021). "Notably, FAL1 promotes cell invasion in part via modulation of Bcl-2, TGF-β1, p65, and PCNA expression in colon cancer cells." (PMID 33246471, 2020). "In colon cancer development, KIAA0125 may contribute via the regulation of BCL2 expression by sponging hsa-miR-29b-3p or regulating PI3K-Akt signaling." (PMID 32607130, 2020). "Moreover, in colon cancer in vitro and in vivo, ART induced apoptosis by concomitantly increasing the expression of PARP-1 and Bax and decreasing Bcl-2." (PMID 33316936, 2020). "Our results implied that EGLP might promote colon cancer cells apoptosis via the regulation of p-Akt1/P-ERK and Bax/Bcl-2 protein expression." (PMID 32495637, 2020). "Utilizing HCT116 colon carcinoma and stem‐like GBM cells, we found that inhibition of Bcl‐xL was most relevant to enhance the apoptotic effects of LXR agonists, followed by Mcl‐1 and Bcl‐2 inhibition (and EV3A and B)." (PMID 31468706, 2019). "Tra2β protein interacts with the BCL2 3′-UTR and promotes abnormal growth of colon cancer cells." (PMID 31311954, 2019). "Interestingly, we found that many of the DEGs and their regulators were prognostic markers for colon cancer, including CEBPB, PPARGC1, STAT3, MTOR, BCL2, JAK2, and CDK1." (PMID 31186640, 2019). "Results of this profiling identified strong dependence on BCLXL regardless of induced BCL2 protein expression in 5-FU-resistant HT-29 cells among three 5-FU-resistant colon cancer cell lines." (PMID 31638265, 2019). "The mechanisms by which miR-125 regulate CRC forms a complex network, miR-125 could negatively modulate BCL2, BCL2L12, and Mcl-1, and down-regulated miR-125 promoted colon cancer cell proliferation and inhibited apoptosis." (PMID 31782506, 2019). "Treatment of colon cancer cells with 15-hydroxy-eicosatetraenoic acid (15S-HETE), an endogenous ligand for PPARγ, arrests the growth of colon cancer cells via a PPARγ dependent pathway involving increased expression of KLF10 and decreased Bcl-2 (B cell lymphoma 2) expressions." (PMID 29799499, 2018). "Importantly, two key genes in apoptosis and stemness, BCL2 and ABCG2, were also upregulated in EP300-knockout colon carcinoma cells and their paclitaxel-resistant derivatives." (PMID 28341962, 2017).
colon carcinoma (continued). "Our results suggest that STAT1, Bax, and Bcl-2 could be involved in the antiproliferative and pro-apoptotic effects of MG and silencing of GLOI in colon cancer cells." (PMID 28903386, 2017). "Furthermore, when PRDX2 was overexpressed in colon cancer cells, we found increased p-AKT protein expression and reduced Bcl-2/Bax protein expression." (PMID 28432271, 2017). "In human colon cancer SNU-C4 cells, the treatment of red wine polyphenols (100 ìg/mL) induced apoptosis via up-regulation of caspase-3 activity and modulation of the BCL-2 family (Bax, Bcl-2)." (PMID 27231920, 2016). "Similar results were observed in both RCC cell lines after treatment with DIM-C-pPhOH or DIM-C-pPhCO2Me, confirming that the NR4A1 antagonists inhibited NR4A1-regulated expression of survivin, bcl-2 and EGFR in ACHN and 786-O cells as previously reported in pancreatic, lung and colon cancers." (PMID 26035713, 2015). "Minoo's study of 399 CRCs showed that TOPK could be a marker of tumor in colon cancer in combination with CDX2, CD44v6, CD44s, nuclear ß-catenin, pERK, APAF-1, E-cadherin, p21, and bcl2." (PMID 25881543, 2015). "In colon cancer, NF-kappaB plays an anti-apoptosis role by many means like, by inhibiting the ROS pathways, by inhibiting JNK cascade and by inducing the expression of anti-apoptotic genes Bcl-2, Bcl-x and cIAPs." (PMID 25157570, 2014). "However, no WWOX-induced changes were observed in the transcription of apoptosis-related genes (BAX, BCL2, BIRC5), whose expression was observed to correlate with WWOX in colon tumour specimens and other cancer tissues." (PMID 24938873, 2014). "In addition, we have recently demonstrated that miR-143 overexpression significantly increases in vitro HCT116 colon cancer cell sensitivity to 5-FU, with a marked decrease in ERK5, NF-κB, and Bcl-2 steady-state levels." (PMID 21901135, 2011). "MAT2A overexpression in liver and colon cancer increases tumor survival and chemo-resistance, by a mechanism involving B-cell lymphoma 2 (BCL-2) transcription, acting directly as a transcription factor that transactivates the BCL-2 promoter, and also stabilizing the BCL-2 protein." (PMID 39941901, 2025). "Moreover, in colon cancer, miR-34a has been shown to inhibit the expression of numerous ATP-binding cassette (ABC) transporters such as MRP2, P-gp and BCRP, as well as antiapoptotic genes like Bcl-2, all of which contribute to chemoresistance." (PMID 40805201, 2025). "Moreover, YAP-1 overexpression in our study may suppress autophagy in colon cancer cells through elevated BCL-2 levels since YAP and TEAD cooperation promotes BCL-2 production, potentially enhancing cell survival by deterring autophagy-related cell death." (PMID 38755413, 2024). "In the cell culture, LS174t colon cancer cells were treated with OB extract, CuNPs, and OB-coated CuNPs with and without different radiation levels in order to assess cell viability, through the MTT assay, and the pro-apoptotic BAX and anti-apoptotic BCL2 expressions, through qPCR assay." (PMID 39044767, 2024). "Anticancer activity on colon cancer cells was measured using the 3-(4,5-dimethylthiazol-2-yl)-2,5-diphenyltetrazolium bromide (MTT) test and cysteine aspartic acid protease-3 (caspase 3), B-cell lymphoma 2 (Bcl-2), and B-cell lymphoma-extra large (Bcl-xL) mRNA expressions." (PMID 38629020, 2024).